MMP9 (matrix metallopeptidase 9)
Diseases named in the same sentence as MMP9 in open-access papers (continued):
Sharing a sentence is not in itself a finding about the gene and the disease.
dilated cardiomyopathy (14 papers, 2014 to 2025). Cardiomyopathy which is characterized by dilation and contractile dysfunction of the left and right ventricles. "Disruption of the major compatibility system with loss of myosin filaments and sarcomere disarrangement underlies the pathomechanism of dilated cardiomyopathy, with MMP9 also contributing." (PMID 37512106, 2023). "Although MMP9/2 represents only a small fraction of the extensive family of MMPs, its specific inhibition affects the key processes that culminate in the attenuation of VO progression to dilated cardiomyopathy and its associated HFrEF." (PMID 32271823, 2020). "MMP9 and its inhibitors can be considered new predictors of dilated cardiomyopathy and used to evaluate treatment effectiveness in patients of different ages." (PMID 36582740, 2022). "Circulating MMP-9 has also been shown to be an effective marker of heart failture and dilated cardiomyopathy." (PMID 32321550, 2020). "Increased levels of matrix proteases such as MMP2 and MMP9 were observed in heart tissue obtained from a patient with dilated cardiomyopathy." (PMID 30116150, 2018). "Increased MMP2 and MMP9 levels are known in patients with dilated cardiomyopathy." (PMID 37512106, 2023). "In addition, MMP9 tissue inhibitor metalloproteinase (TIMP-1) ratio was increased 3–5 times in patients with dilated cardiomyopathy." (PMID 34685620, 2021). "By contrast, persistent presence of MMP-9 contributes to inflammation and tissue destruction in many disease states including chronic wounds, heart failure, rheumatic arthritis, fibrotic lung disease, dilated cardiomyopathy, multiple sclerosis, asthma, and cancer." (PMID 25364719, 2014).
endotoxemia (14 papers, 2015 to 2025). "CD11bhigh GR-1high neutrophils are not only the main source of MMP-9, but also the recruitment of neutrophils play important roles in MMP-9-associated tissue damages during endotoxemia." (PMID 31213027, 2019). "Our findings demonstrated that the novel fungal sesquiterpene HA could provide new opportunities for the development of different strategies on pro-inflammatory cytokines- and MMP-9-associated diseases, such as endotoxemia." (PMID 31213027, 2019). "The plasma MMP-9 measurements were shown to increase after lipopolysaccharide infusion in horses, and peritoneal MMP-9 concentrations were shown to be a valuable biomarker to assess endotoxemia in equine colic." (PMID 38136813, 2023). "These authors suggest that the increase in plasma MMP-2 activity is related to endotoxemia, and that the increase in urinary MMP-9 complex and pro-MMP-9 activities is indicative of AKI." (PMID 36230418, 2022). "The protective effect of hydrogen on lungs in our endotoxemia model was realized through the upregulation of Trx1 expression with inhibition of TF/MMP-9 activation and the inflammatory response." (PMID 33767697, 2021). "Inhalation of hydrogen decreased tissue factor (TF) expression and MMP-9 activity, while Trx1 expression was increased in the lungs and serum of endotoxemia mice." (PMID 33767697, 2021). "In summary, we demonstrated that hydrogen attenuated endotoxin-induced lung injury and improved the survival rate of endotoxemia mice by increasing Trx1 expression to decrease TF expression and MMP-9 activity." (PMID 33767697, 2021). "Striking contributions of MMP-9 to acute inflammation are the induction of leukocytosis and the detrimental effects in mouse models for endotoxemia." (PMID 32645949, 2020). "Since in previous studies, it was shown that induction of endotoxemia results in an increase of MMP-9 in blood and in organs affected by systemic inflammations, we also investigated the presence of MMP-9." (PMID 32645949, 2020). "However, murine CB2 receptor depletion increased neutrophil recruitment in a murine model of endotoxemia, probably mediated by expanded MMP-9 secretion." (PMID 36178662, 2023). "The effect of ongoing inflammatory processes and endotoxemia need to be further evaluated as this may be a major influencing factor on MMP-9 measurements." (PMID 38136813, 2023). "Our hypothesis that there is a regression of local and systemic MMP-9 concentrations and endotoxemia in equine colic was confirmed." (PMID 33488296, 2021). "Leukocytes-mediated MMP-9 production and secretion could be induced by inflammatory response, in particular endotoxemia, CD11bhigh GR-1high neutrophils are the main producers of MMP-9." (PMID 31213027, 2019). "Indeed, our laboratory recently demonstrated that neutrophil infiltration to the spleen is regulated by CB2via MMP-9 reduction in a low dose endotoxemia model, and others have found higher MMP-9 levels in atherosclerotic lesions from CB2−/− animals." (PMID 30799631, 2019). "Moreover, we observed a CB2-dependent suppression of neutrophil recruitment to the spleen at the 2-hour time point of the low-dose endotoxemia model which coincides with elevated levels of MMP-9 in the serum of the animals." (PMID 28852269, 2017). "Taken together, LPS induced significant upregulation and activation of MMP-2 and MMP-9 in the rat endotoxemia model, which may contribute to the development of vascular leaking through shedding endothelial surface glycocalyx complex." (PMID 26199464, 2015). "Dexamethasone and doxycycline may protect endothelial cells from injury and glycocalyx from shedding through suppressing MMP-2 and MMP-9 in LPS-induced rat endotoxemia model." (PMID 26199464, 2015). "Besides, enhanced MMP-9 circulating levels have been described in an endotoxemia model." (PMID 33891967, 2021).
endotoxemia (continued). "Upon induction of endotoxemia, neutrophils migrate from the bone marrow to the periphery, resulting in degranulation of MMP-8 (neutrophil collagenase) and MMP-9 into the circulation and in vital organs such as the lungs and liver." (PMID 32645949, 2020). "In the current study, therefore, using an animal model of endotoxemia, role of MMP-2 and MMP-9 in mediating LPS-induced degradation of ZO-1 and syndecan-1 was investigated." (PMID 26199464, 2015).
Lewis lung carcinoma (14 papers, 2004 to 2023). "MMP9 is similarly associated with the metastasis of Lewis lung carcinoma cells in mice downstream of VEGFR-1 activation." (PMID 29876004, 2018). "However, there is a small amount of evidence demonstrating the association among VEGF and MMP2 and MMP9 in Lewis lung carcinoma cells." (PMID 23226772, 2012). "Sublethal radiation induces matrix metalloproteinase 9 (MMP-9)-mediated radioresistance in Lewis lung carcinoma (LLC) cells and their metastatic dissemination." (PMID 32143669, 2020). "In this study, we showed that sublethal radiation doses increase phosphorylation of EGFR, HER2, and downstream Akt, ERK, and p38, and increase MMP-9 production in Lewis lung carcinoma (LLC) cells in vitro." (PMID 32143669, 2020). "MMP‐9 was also demonstrated to promote cell invasion and metastasis of Lewis lung carcinoma." (PMID 38012058, 2023).
pancreatic adenocarcinoma (14 papers, 2004 to 2024). "The aim of the study was to evaluate the expression of MMP-2, MMP-7, and MMP-9 in normal ducts, tumor pancreatic adenocarcinoma cells, and peritumoral stroma in correlation with clinicohistopathological parameters." (PMID 27429508, 2016). "Duxbury & Whang found RRM2 induced NFκB activation of MMP9 and enhanced cellular invasiveness in pancreatic adenocarcinoma cells." (PMID 26001082, 2015). "Expression of COX-2 and MMP-9 mRNA varied in pancreatic adenocarcinomas, and the mRNA level of COX-2 was correlated positively with MMP-9." (PMID 21760774, 2011). "COX-2 and MMP-9 mRNA were initially detected in 16 pancreatic adenocarcinomas by RT-PCR, and then their expression was found to have varied in these cancers." (PMID 21760774, 2011). "Modulation of c-Src tyrosine kinase activity alters MMP-9 activity in a variety of tumour cell types, including pancreatic adenocarcinoma cells." (PMID 15316565, 2004). "Andecaliximab (GS-5745, a monoclonal antibody targeting MMP9) had been evaluated in several clinical trials for indications including advanced gastric and gastroesophageal junction adenocarcinoma and advanced pancreatic adenocarcinoma." (PMID 36569935, 2022). "Therefore, the aim of our study was to evaluate the immunohistochemical expressions of MMP-2, MMP-7, and MMP-9 in the normal pancreas, pancreatic adenocarcinoma tumor cells, and stromal cells in correlation with clinicopathological features." (PMID 27429508, 2016). "Serum MMP-9 measurement might be helpful in discriminating pancreatic adenocarcinoma from chronic pancreatitis and healthy controls." (PMID 18706098, 2008). "The findings suggest that serum measurement of MMP-9 or other up-regulated proteins in cancerous pancreatic juice might be helpful in the diagnosis of pancreatic adenocarcinoma and deserve further investigation." (PMID 18706098, 2008). "We have previously shown that the Src family kinase inhibitor pyrazolopyrimidine (PP2) inhibits pancreatic adenocarcinoma cellular invasiveness in association with dephosphorylation of the prototype Src family kinase, c-Src, and suppression of MMP-2 and MMP-9 activities." (PMID 15316565, 2004). "Stimulation of the CCR7-expressing pancreatic adenocarcinoma-derived cell line, PANC1, with CCL19 led to enhanced expression of p-ERK, p-AKT, N-cadherin and MMP-9, markers of EMT progression, further implicating CCR7 in the metastatic progression of pancreatic adenocarcinomas." (PMID 35203305, 2022).
Peri-Implantitis (14 papers, 2019 to 2025). An inflammatory process with loss of supporting bone in the tissues surrounding functioning DENTAL IMPLANTS. "Investigating cytokine levels in PICF revealed that IL-1β and MMP-9 levels tended to be the highest in the high-risk group, suggesting that the development of peri-implantitis converges from innate immunity to specific immunity." (PMID 39555067, 2024). "MMP-9 is especially tricky to assign a certain role in peri-implantitis, because when the levels are found to be high, together with MMP-8 and -13, there tends to be more bone loss around the diseased implant." (PMID 37232785, 2023). "MMP-9 is involved in the progression of peri-implantitis and is correlated with LOX-1 and the ERK1/2-mediated signaling pathway." (PMID 34931168, 2021). "This case-control study evaluated the gene expression levels of interleukin(IL)-4, macrophage inflammatory protein type 1 alpha (MIP-1α), andmetalloproteinase (MMP)-9, factors involved in the formation of giant cells inhealthy peri-implant tissue and peri-implantitis." (PMID 37466520, 2023). "Finally, the potential target genes, namely, IL-6, TLR4, FN1, IL-1β, CXCL8, MMP-9, and SPP1, were found to be associated with peri-implantitis, and our results were consistent with those of previous studies." (PMID 34931168, 2021). "Additionally, the downregulation of MMP9 and LOX-1 expression by metalloproteinase inhibitors indicates that Erk1/2, LOX-1, and MMP9 could serve as potential therapeutic targets for treating peri-implantitis." (PMID 39555067, 2024). "However, the regulatory mechanisms of MMP-9 in peri-implantitis need to be well elucidated." (PMID 34931168, 2021). "The intersecting genes, including IL6, TLR4, FN1, IL1β, CXCL8, MMP9, and SPP1, were revealed as potential genetic biomarkers and target genes of peri-implantitis." (PMID 34931168, 2021). "We found that IL-6, TLR4, FN1, IL-1β, CXCL8, MMP-9, and SPP1 might be used as potential biomarkers for the diagnosis of peri-implantitis." (PMID 34931168, 2021). "The LOX-1/MMP-9 signaling pathway and OPN may be potential drug targets to decrease the levels of proinflammatory cytokines and increase apoptosis in peri-implantitis." (PMID 34931168, 2021). "This study provides supportive evidence that IL6, TLR4, FN1, IL1β, CXCL8, MMP9, and SPP1 might be used as potential target biomarkers for peri-implantitis which may provide further therapeutic potentials for peri-implantitis." (PMID 34931168, 2021). "In this study, an aMMP-8 peri-implant sulcular fluid point-of-care-test diagnosed peri-implantitis and healthy implants far more accurately than bleeding-on-probing or the other biomarkers, such as polymorphonuclear (PMN)/neutrophil elastase, myeloperoxidase and MMP-9." (PMID 32764436, 2020).
pulmonary TB (14 papers, 2011 to 2025). "Neutrophil-associated metalloproteinases MMP8 and MMP9 both mediate matrix destruction during pulmonary TB and contribute to subsequent fibrosis formation." (PMID 36674664, 2023). "We have also explored the specifically expressed serum proteins in TB patients by iTRAQ-2DLC-MS/MS, and found serum protein S100A9, SOD3, and MMP9 as new potential diagnostic biomarkers for pulmonary TB." (PMID 26198726, 2015). "In particular, a recent report revealed that MMP-1(-1607G), a member of MMP-9, and its polymorphism could act as a risk factor for fibrosis after pulmonary tuberculosis in Taiwan." (PMID 38235425, 2023). "An increase in MMP-8 and MMP-9 are seen in pulmonary TB and reflects the severity of the destructive process." (PMID 37319185, 2023). "MMP-9 expression remarkably increases in both lungs of patients with pulmonary tuberculosis and lymph nodes of patients with lymphatic tuberculosis." (PMID 35095838, 2021). "Pulmonary tuberculosis in vitro studies suggest that vitamin D blunts MMP-9 expression by inhibition of c-Jun-N-terminal kinase(JNK) and NFkappaB signaling cascades." (PMID 21600051, 2011). "In addition, studies have found that the content of MMP-1, MMP-9, and other matrix metalloproteinases in bronchoalveolar lavage fluid of pulmonary tuberculosis patients is significantly increased." (PMID 35388750, 2023). "Smokers with pulmonary tuberculosis had higher levels of MMP-9 in their bronchoalveolar lavage." (PMID 37332754, 2023). "Increased MMP-9 protein expression has also been observed in lungs of six patients with pulmonary tuberculosis and in lymph nodes of six patients with lymphatic tuberculosis, compared with that in patients of chronic inflammation by immunohistochemistry analysis." (PMID 35095838, 2021). "Infection with S. stercoralis in the context of active pulmonary TB was associated with significantly lower levels of MMP-1 (GM of 5.3 ng/ml in ATB vs. 3.9 ng/ml in ATB+Ss) and MMP-9 (GM of 646.4 ng/ml in ATB vs. 331.2 ng/ml in ATB+Ss) - when compared to Ss-uninfected individuals with active TB." (PMID 25375117, 2014). "Interestingly, we observed significantly lower levels of both neutrophils and MMP9 in TB/HIV co-infection compared to new pulmonary TB, likely due to the impaired production of neutrophils resulting from low CD4+ T-lymphocyte count and viability in co-infected individuals." (PMID 40574839, 2025). "Similarly, the results from this study suggest that matrix metalloproteinases (i.e., MMP8 and MMP9) are upregulated in TB sputum vs. non-TB sputum, which is in agreement with previous reported studies that implicated these enzymes in active pulmonary TB." (PMID 40981203, 2025). "A study on patients with smoking-related pulmonary tuberculosis discovered that the proportion of M2 macrophages in the bronchoalveolar lavage fluid of pulmonary tuberculosis-smokers was significantly increased, accompanied by upregulation of inflammatory factors such as MMP9 and MMP12." (PMID 41562082, 2025). "The collagenases, MMP-1 and MMP-8, were elevated in plasma of patients with pulmonary TB relative to healthy controls, and MMP-7 (matrilysin) and MMP-9 (gelatinase B) were also increased." (PMID 25635689, 2015). "In this study, serum levels of interferon gamma (IFN-γ), matrix metalloproteinases 1 and 9 (MMP-1 and MMP-9, respectively), and periostin were compared between 40 pulmonary tuberculosis (PTB) and 28 non-tuberculous pneumonia (non-PTB) patients." (PMID 31917802, 2020).